ENG (endoglin)
Description:
Vascular endothelium glycoprotein that plays an important role in the regulation of angiogenesis. Required for normal structure and integrity of adult vasculature. Regulates the migration of vascular endothelial cells. Required for normal extraembryonic angiogenesis and for embryonic heart development (By similarity). May regulate endothelial cell shape changes in response to blood flow, which drive vascular remodeling and establishment of normal vascular morphology during angiogenesis (By similarity). May play a critical role in the binding of endothelial cells to integrins and/or other RGD receptors. Acts as a TGF-beta coreceptor and is involved in the TGF-beta/BMP signaling cascade that ultimately leads to the activation of SMAD transcription factors. Required for GDF2/BMP9 signaling through SMAD1 in endothelial cells and modulates TGFB1 signaling through SMAD3.
Synonyms: CD105; END; HHT1; ORW1; formerly ORW
Tractability: Antibody: a drug acting on it is in phase 2 or 3 trials; UniProt places it where antibodies can reach, with high confidence; its Gene Ontology location is reachable by antibodies, with high confidence; UniProt predicts a signal peptide or a membrane-spanning region; the Human Protein Atlas places it where antibodies can reach. PROTAC: its protein half-life has been measured.
Gene: Protein-coding gene on chromosome 9 (127,811,130 to 127,855,232, reverse strand). Ensembl gene ENSG00000106991.
Subcellular location: Cell membrane
Subcellular location (Human Protein Atlas): Plasma membrane
Gene Ontology:
Molecular function: BMP binding; coreceptor activity; galactose binding; glycosaminoglycan binding; identical protein binding; protein binding; signaling receptor activator activity; transforming growth factor beta binding; type I transforming growth factor beta receptor binding; type II transforming growth factor beta receptor binding; activin binding; transmembrane signaling receptor activity; protein homodimerization activity
Biological process: central nervous system vasculogenesis; negative regulation of cell migration; positive regulation of BMP signaling pathway; positive regulation of phosphatidylinositol 3-kinase/protein kinase B signal transduction; positive regulation of SMAD protein signal transduction; regulation of DNA-templated transcription; regulation of transforming growth factor beta receptor signaling pathway; transforming growth factor beta receptor signaling pathway; vasculogenesis; artery morphogenesis; atrial cardiac muscle tissue morphogenesis; atrioventricular canal morphogenesis; BMP signaling pathway; branching involved in blood vessel morphogenesis; cardiac atrium morphogenesis; cardiac ventricle morphogenesis; dorsal aorta morphogenesis; endocardial cushion morphogenesis; endocardial cushion to mesenchymal transition; epithelial to mesenchymal transition involved in endocardial cushion formation; heart looping; negative regulation of gene expression; outflow tract septum morphogenesis; positive regulation of epithelial to mesenchymal transition involved in endocardial cushion formation; positive regulation of transcription by RNA polymerase II; and 9 more
Cellular component: external side of plasma membrane; extracellular region; focal adhesion; plasma membrane; receptor complex; cell surface; endothelial microparticle
Genetic constraint (gnomAD): Loss-of-function variants: 17 observed, 68.24 expected, observed/expected ratio (o/e) 0.25, 90% interval 0.17 to 0.37. The upper end of that interval is the gene's LOEUF score, 0.37, which puts it in group 1 of 6, group 1 being the genes least tolerant of losing a copy. Missense variants: 749 observed, 851.69 expected, observed/expected ratio (o/e) 0.88, 90% interval 0.83 to 0.93. Synonymous variants: 360 observed, 362.38 expected, observed/expected ratio (o/e) 0.99, 90% interval 0.91 to 1.08.
Gene-disease validity (ClinGen):
ClinGen rates the evidence that ENG causes each of these diseases.
telangiectasia, hereditary hemorrhagic, type 1 (autosomal dominant): Definitive.
juvenile polyposis syndrome (autosomal dominant): Limited. Juvenile gastrointestinal polyposis (JIP) is a rare condition characterized by the presence of juvenile hamartomatous polyps in the gastrointestinal (GI) tract.
Homologues: Orthologues: chimpanzee ENG (99% identical), macaque ENG (94% identical), dog ENG (74% identical), rat Eng (72% identical), mouse Eng (72% identical), guinea pig ENG (69% identical), pig ENG (68% identical), rabbit ENG (62% identical), tropical clawed frog eng (23% identical). Paralogues in human: TGFBR3 (26% identical), TGFBR3L (6% identical).
Diseases named in the same sentence as ENG in open-access papers:
ENG is named in the same sentence as 398 diseases in open-access papers, as found by Europe PMC text mining. Sharing a sentence is not in itself a finding about the gene and the disease. The quoted sentences say what the papers report.
hereditary hemorrhagic telangiectasia (190 papers, 2008 to 2026). A disorder of angiogenesis leading to arteriovenous dilatations: cutaneo-mucosal hemorrhagic telangiectasias and visceral shunting. "ENG is implicated in several cardiovascular disorders including hereditary haemorrhagic telangiectasia, pulmonary arterial hypertension (PAH) and preeclampsia." (PMID 41476036, 2025). "Mutations in ACVRL1 (or endoglin) can cause the vascular disease hereditary hemorrhagic telangiectasia type 2 (HHT2), which is associated with abnormal blood vessel structures and increased risk of bleedings." (PMID 41378712, 2025). "The ENG gene encodes endoglin, with loss-of-function mutations causing hereditary hemorrhagic telangiectasia type 1 (HHT1), whereas ACVRL1 encodes ALK1, whose pathogenic variants underlie HHT type 2 (HHT2)." (PMID 40933708, 2025). "Hereditary Hemorrhagic Telangiectasia(HHT) is an autosomal dominant disease caused by mutations in the human endoglin gene (ENG), which encodes for the protein by the same name." (PMID 40078403, 2025). "Loss of BMP-9 or mutations in the endoglin gene (ENG) can lead to vascular disorders such as arteriovenous malformations (AVMs) or hereditary hemorrhagic telangiectasia (HHT)." (PMID 41378712, 2025). "Homozygous mutations in mice result in embryonic lethality, and certain point mutations in human ENG are linked to hereditary hemorrhagic telangiectasia (HHT)." (PMID 38534334, 2024). "Mutations in ALK1 result in type 2 hereditary hemorrhagic telangiectasia; mutations in ENG and SMAD4 result in vascular malformation." (PMID 39022219, 2024). "Clinically, hereditary hemorrhagic telangiectasia type 1 (HHT1; OMIM: 187300) is caused by mutations of the ENG gene, whereas hereditary hemorrhagic telangiectasia type 2 (HHT2; OMIM: 600376) is caused by mutations of the ALK1 gene." (PMID 38540362, 2024). "Mutations in ENG lead to hereditary hemorrhagic telangiectasia (HHT), an autosomal dominant vascular disease." (PMID 38242992, 2024). "A vascular malformations disease, hereditary hemorrhagic telangiectasia type-1 (HHT-1) is related to deficiency in Endoglin expression." (PMID 36594057, 2023). "Intriguingly, mutations in ACVRL1 and ENG are more commonly associated with hereditary hemorrhagic telangiectasia (HHT) than PAH." (PMID 35434863, 2023). "Mutations in the gene encoding Endoglin (ENG) have been associated with hereditary hemorrhagic telangiectasia type 1 (HHT1), an autosomal dominant inherited disease that is generally characterized by vascular malformation." (PMID 35281255, 2022). "Patients heterozygous for ENG or ALK1 mutations develop the vascular disorder known as hereditary haemorrhagic telangiectasia (HHT)." (PMID 36250069, 2022). "The mutations in ACVRL1 or ENG genes primarily lead to PAH associated with hereditary hemorrhagic telangiectasia (HHT), which is a rare autosomal dominantly genetic disease." (PMID 36506323, 2022). "Mutations in endoglin resulting in haploinsufficiency are the cause of the autosomal dominant vascular disorder hereditary hemorrhagic telangiectasia type 1 (HHT1)." (PMID 33670533, 2021). "Mutations in endoglin (ENG) and activin receptor-like kinase 1 (ACVRL1) (encoding ALK1) have been linked to a human vascular disorder hereditary hemorrhagic telangiectasia (HHT1 and HHT2, respectively), often resulting in arteriovenous malformations (AVM)." (PMID 32183218, 2020). "Mutations in the endoglin gene cause hereditary hemorrhagic telangiectasia (HHT or Osler-Weber-Rendu syndrome), a disease characterized by arteriovenous malformations." (PMID 33375670, 2020). "Loss of function mutations in either ENG or ALK1 genes lead to the inherited vascular disorder hereditary haemorrhagic telangiectasia (HHT), characterised by arteriovenous malformations (AVMs)." (PMID 32506200, 2020).
hereditary hemorrhagic telangiectasia (continued). "Mutations in endoglin lead to hereditary hemorrhagic telangiectasia —an inherited vascular disorder characterized by AVMs, which are localized direct connections between arteries and veins." (PMID 31805812, 2020). "Loss of function mutations in either ENG or ALK1 genes account for the vast majority of cases of hereditary haemorrhagic telangiectasia (HHT)." (PMID 32506200, 2020). "Mutations in endoglin lead to hereditary hemorrhagic telangiectasia—a disease characterized by arteriovenous malformations (AVMs)." (PMID 31805812, 2020). "There were 507 reported variations in the ENG gene in the Hereditary Hemorrhagic Telangiectasia Mutation Database of Utah University." (PMID 31594285, 2019). "Heterozygous LOF mutations of ENG cause hereditary hemorrhagic telangiectasia type 1 (HHT1), also known as Osler–Weber–Rendu disease, a rare autosomal dominant condition characterized by telangiectasias and arteriovenous malformations." (PMID 31749832, 2019). "Heterozygous mutations in the endoglin gene (ENG) cause hereditary hemorrhagic telangiectasia type 1, a vascular disease that presents with nasal and gastrointestinal bleeding, skin and mucosa telangiectases, and arteriovenous malformations in internal organs." (PMID 31540324, 2019). "Mutations in the endoglin gene (ENG) cause hereditary hemorrhagic telangiectasia type 1 (HHT1), characterized by arteriovenous malformations (AVMs) in different organs." (PMID 30108051, 2018). "The endothelial receptor endoglin is involved in inflammation through integrin-mediated leukocyte adhesion and transmigration; and heterozygous mutations in the endoglin gene cause hereditary hemorrhagic telangiectasia type 1." (PMID 29080903, 2018). "Hereditary hemorrhagic telangiectasia (HHT) is caused by mutations in endoglin or activin receptor-like kinase-1 (ACVRL1/ALK1) genes and is an autosomal dominant vascular disorder." (PMID 30406106, 2018). "Hereditary Hemorrhagic Telangiectasia type-1 (HHT1) is a genetic vascular disorder caused by haploinsufficiency of the TGFβ co-receptor endoglin." (PMID 29253907, 2017). "Mutations in the ENG gene are associated with type 1 hereditary hemorrhagic telangiectasia (HHT), also known as Osler-Rendu-Weber Syndrome." (PMID 29098173, 2017). "Hereditary Hemorrhagic Telangiectasia type 1 (HHT1) is a haploinsufficient genetic vascular disorder caused by mutations in the transforming growth factor beta (TGFβ) co-receptor endoglin (CD105)." (PMID 29253907, 2017). "In human, functional haploinsufficiency of ENG gene causes type I hereditary hemorrhagic telangiectasia (HHT1), an autosomal dominant disorder." (PMID 29098173, 2017). "ALK1 and its co-receptor ENG are co-expressed on the surface of endothelial cells during active angiogenesis, and a mutation in either one results in hereditary hemorrhagic telangiectasia (HHT), an autosomal dominant vascular dysplasia syndrome." (PMID 27248821, 2016). "Endoglin is involved in angiogenesis and vessel homoeostasis; an endoglin gene mutation leads to hereditary hemorrhagic telangiectasia." (PMID 27110824, 2016). "Mutations in ENG are responsible for the Hereditary Hemorrhagic Telangiectasia type 1 (HHT1) or Rendu-Osler-Weber syndrome." (PMID 27010826, 2016). "Hereditary Hemorrhagic Telangiectasia (HHT) is an autosomal dominant disorder resulting from loss of function mutations predominantly in ENG (HHT type 1) or ACVRL1 aka ALK1 (HHT type 2)." (PMID 25815003, 2015). "Rendu-Osler-Weber disease is an autosomal dominant hereditary condition, caused by a mutation in the gene encoding endoglin (ENG), a transforming growth factor-beta binding protein that has an angiogenic function, on chromosome 9q34.11." (PMID 24707424, 2014). "Mutations in endoglin have been found to be a causal factor in hereditary hemorrhagic telangiectasia (HHT), a disease characterized by the malformation of vascular structure." (PMID 25361902, 2014).
hereditary hemorrhagic telangiectasia (continued). "Mutations in the endoglin gene (ENG) are responsible for ∼50% of all cases with hereditary hemorrhagic telangiectasia (HHT)." (PMID 25709613, 2014). "Germline mutations in endoglin cause the genetic disease hereditary hemorrhagic telangiectasia, highlighting endoglin’s role as a key regulator of endothelial cell motility, invasion, and proliferation." (PMID 23967299, 2013). "Mutations in the endoglin gene leading to endoglin haploinsufficiency are the cause of the Hereditary Hemorrhagic Telangiectasia (HHT) type 1." (PMID 23336009, 2013). "Mutations in the endoglin gene can lead to hereditary hemorrhagic telangiectasia (HHT) and defective angiogenesis." (PMID 23349951, 2013). "Mutations in the human ENDOGLIN gene (ENG) are responsible for Hereditary Hemorrhagic Telangiectasia (HHT) type 1, a disease characterized by frequent nose bleeds, telangiectases on skin and mucosa and arteriovenous malformations in lung, liver and brain." (PMID 22347366, 2012). "In congenital PAVF, 70% of patients have a history of hereditary hemorrhagic telangiectasia (HHT) which is caused by mutations in Endoglin (HHT1) and ALK1 (HHT2)." (PMID 22925775, 2012). "The human endoglin gene has been localized to chromosome 9q34ter, and it is mutated in the Rendu-Osler-Weber syndrome or hereditary hemorrhagic telangiectasia type 1 (HHT1)." (PMID 21171985, 2010). "Interestingly, both molecules identified as cargoes of filopodia-regulating exosomes are associated with disease: endoglin with hereditary hemorrhagic telangiectasia, and THSD7A with a kidney disease called secondary membranous nephropathy." (PMID 41532547, 2026). "Indeed, mutations in endoglin are a frequent cause of hereditary hemorrhagic telangiectasia – a disease in which abnormal vascular structures are formed in the skin, mucous membranes, and some organs." (PMID 41532547, 2026). "BMP9 is an important mediator of vascular quiescence, and the loss-of-function mutations in the BMP9—ENG—ALK1 signaling pathway lead to hereditary hemorrhagic telangiectasia (HHT), an inherited disorder characterized by vascular dysplasia and potential bleeding tendencies." (PMID 39199400, 2024). "Endoglin (ENG) mutation causes type 1 hereditary hemorrhagic telangiectasia (HHT1)." (PMID 39200156, 2024). "ENG, as a coreceptor of TGF-β, is an important modulator of vascular homeostasis: ENG deficiency is embryonically lethal, and heterozygous mutations within the ENG gene result in hereditary hemorrhagic telangiectasia, a vascular disease with arteriovenous malformations and bleeding complications." (PMID 36672223, 2023). "Hereditary Hemorrhagic Telangiectasia (HHT) is an autosomal dominant vascular dysplasia caused by mutations in genes involved in the TGFβ-BMP receptor signaling pathway: ENG (HHT type 1), ACVRL1 (HHT type 2) and MADH4 (HHT overlap syndrome with Juvenile Polyposis)." (PMID 32032395, 2020). "Heterozygous mutations in the human ENDOGLIN gene (ENG) cause hereditary hemorrhagic telangiectasia (HHT) type 1, a vascular disease associated with nasal and gastrointestinal bleeds, telangiectases on skin and mucosa and arteriovenous malformations in the lung, liver, and brain." (PMID 31540324, 2019). "Moreover, ALK1 and ENG gene mutations lead to similar syndromic diseases, namely, hereditary hemorrhagic telangiectasia type 2 and hereditary hemorrhagic telangiectasia type 1, respectively." (PMID 31189661, 2019). "ENG is also a recognized marker of angiogenesis and mutations in the endoglin gene are responsible for Hereditary Hemorrhagic Telangiectasia (HHT) type 1, a vascular disease characterized by defective angiogenesis, arteriovenous malformations, telangiectasia, and epistaxis." (PMID 30761306, 2019). "Mutations in ENG are responsible for the Hereditary Hemorrhagic Telangiectasia type 1 (HHT1)." (PMID 27010826, 2016).